IL10 (interleukin 10)
Diseases named in the same sentence as IL10 in open-access papers (continued):
Sharing a sentence is not in itself a finding about the gene and the disease.
tumor (continued). "Levels of IL-10 were increased in IV-treated mice compared to s.c. treated; ideally levels of IL-10 should be suppressed by a successful therapy as regulatory T cells in the tumour environment often produce IL-10 as a means of suppressing the immune response to tumour cells." (PMID 27412241, 2016). "The TAM and those factors are important parts of the tumor microenvironment, regulating cancer development, which is called the M2 phenotype of macrophage (usually expressing high levels of IL-10, VEGF and Arg-1; whereas expressing low levels of IL-12, IL-23 and iNOS)." (PMID 27107415, 2016). "However, we observed that the anti-inflammatory cytokine IL-10 was upregulated, promoting an IL-10 preponderant microenvironment within the tumor mass." (PMID 26898917, 2016). "Moreover, if the BF-rTK survived in the tumor via IV administration, it would be assumed that BF-rTK stimulated the production of higher concentrations of cytokines (e.g., IL-1α, IL-1β, IL-2, IL-10, IL-17, GM-CSF, and MCP-1)." (PMID 27275821, 2016). "However, the mechanism by which Tregs contribute to tumor infiltration through IL-10 production remains elusive." (PMID 27075020, 2016). "However, stimulation of tumor cells with IL-10-treated MΦ supernatants significantly enhanced MCF-7 proliferation." (PMID 27806101, 2016). "Therefore, we used a neutralizing anti-Nrp-1 Ab18 to treat IL10−/− and WT tumor-bearing mice on days +9 and +12 after B16/F10 implantation." (PMID 27075020, 2016). "In some forms of human tumors, TAMs have also been reported to show defective release of IL-12, and to increase secretion of anti-inflammatory cytokines such as IL-10, to influence tumor progression via the promotion of tumor vascularization, growth, survival, and metastasis." (PMID 27029067, 2016). "Interestingly, it has recently been shown that synergic induction of COX-2 by IFN-γ and TNF-α limits type-1 immune response in tumor microenvironment by concomitant action of IL-10, NOS2, and Indoleamine 2,3-dioxygenase." (PMID 28018318, 2016). "M2 macrophages produce IL-10, which promote tumor progression." (PMID 27018053, 2016). "They hypothesized that this decrease may be due to the inhibitory effects of TGFβ and IL‐10 secreted by NSCLC tumor cells." (PMID 27416962, 2016). "One study reported that the CSF levels of IL-10 in PCNSL patients were correlated with infiltration of tumor associated macrophages (TAM) and TAM cells expressing IL-10, suggesting that CSF IL-10 may be primarily secreted by TAMs27." (PMID 27924864, 2016). "Our data indicate that IL10 is increased in the tumor microenvironment and IL10 knockout inhibits the formation of the tumor microenvironment, indicating that IL10 is crucial for the tumor microenvironment." (PMID 26956044, 2016). "Indeed, our FACS analysis showed that both the IL-12+ M1 and IL-10+ M2 populations were increased in sST2 low-expressing tumours." (PMID 27882929, 2016). "Finally, use of neutralizing antibodies against IL-10 or depleting Tregs both block PAF-mediated augmentation of experimental tumor growth." (PMID 26959112, 2016). "Upregulation of IL-10 has been suggested to be responsible for the persistence of inflammation and might facilitate tumor progression." (PMID 27600085, 2016). "The hypothesis of a direct influence of the tumour on lymphocyte homeostasis is plausible and supported by the capacity of the tumour to secret immunosuppressive cytokines like IL-10 and TGFβ." (PMID 27782813, 2016). "Exogenous addition of IL-10 in DC culture from normal donor upregulated PD-L1 surface expression, while IL-10 blockade with neutralizing antibody reversed upregulated PD-L1 expression in DCs from tumor patients." (PMID 26980944, 2016). "However, both immunosuppressive and anti-tumor effects appear to be active in tumors at all sites to varying degrees, which naturally presents challenges for IL-10-directed immunotherapy." (PMID 26217588, 2015).
tumor (continued). "Other cytokines produced by NK cells, e.g., TNF-α, GM-CSF, IL-10, and IL-13, may be considered for the evaluation of tumor cell sensitivity to NK cell-mediated killing and could be significant predictive markers for therapy effectiveness." (PMID 25674087, 2015). "Ablation of IL-10 increases tumor incidence, growth, and metastasis." (PMID 26006716, 2015). "Interestingly, IL-10 is present in the leucocyte infiltrate of the tumor instead of in the NPC cells." (PMID 25402728, 2015). "The anti-angiogenic effects of IL-10 may also play an important part in inhibiting tumor growth and metastasis." (PMID 26217588, 2015). "Similarly, it has also been described that immunohistochemical expression of COX-2, IL-10 and Ki67 was higher in tumor stromal areas than tumor cell areas." (PMID 26431176, 2015). "However, M2 macrophages, activated by IL-10, IL-13, and so forth, have an immune regulating and suppressive role via multiple ways to promote tumor progression." (PMID 26161392, 2015). "An important strategy of tumor cells to avoid destruction by immune system is to create an immunosuppressive environment by secretion of highly immunosuppressive cytokines such as TGFβ, IL10." (PMID 26464579, 2015). "Besides its tolerogenic properties, IL-10 also exerts anti-angiogenic effects with both tumor promoting and inhibiting results." (PMID 25682197, 2015). "In the case of MCL, it has been observed that stimulation of TLR4—Which was found to be highly expressed in primary MCL samples and cell lines—Resulted in tumor cell proliferation as well as upregulated secretion of soluble immunosuppressive factors IL-6, IL-10 and VEGF." (PMID 25941795, 2015). "The increased frequency of CD14+CD169+IL-10+ macrophages in tumor tissues may create a protumor immunosuppressive microenvironment to promote the progression of CRC." (PMID 26509874, 2015). "Whereas anti-tumor Th1 cells limit tumor progression by enhancing cytotoxic T-cell responses, pro-tumor Th2 cells skew adaptive responses toward humoral immunity via production of cytokines such as IL-4 and IL-10." (PMID 26690220, 2015). "In contrast to these results, some studies suggest that IL-10 is important for tumor rejection." (PMID 26604855, 2015). "In contrast, we find that high baseline IL-10 levels to be correlated with tumor relapse." (PMID 26380086, 2015). "MDSCs represent a diverse population of immature and highly immunosuppressive myeloid cells that accumulate in the tumor, blood, lymph nodes, and bone marrow of tumor-bearing hosts in response to tumor-derived factors, such as IL-6, IL-10, PGE2, TGF-β2, and VEGF." (PMID 26217588, 2015). "Macrophages can be classically activated into M1 cells that express inducible nitric oxidase (iNOS), IL-12 and high levels of co-stimulator molecules while resident tissue macrophages and tumor-associated macrophages are likely to express CD163, 206, arginase and IL-10, a M2 phenotype." (PMID 26509874, 2015). "However, since macrophages have either tumor-promoting or anti-tumor properties depending on cytokine production, intracellular IL-10 was examined as a pro-tumorigenic cytokine and IL-12 as an anti-tumorigenic cytokine known to be produced by macrophages." (PMID 26061815, 2015). "M1, the classically activated MΦ/Mo induced by IFN-γ and bacterial products, display high antigen presentation efficiency due to upregulation of MHCII (HLA-DR) and co-stimulatory molecules (CD80 and CD86), express high levels of IL-12 and low IL-10, and thus activate Tc1/Th1 anti-tumor responses." (PMID 26579227, 2015). "Furthermore, a robust TLR-induced inflammatory response seemed unlikely considering the cytokine milieu of the tumor microenvironment, which contains significant amounts of immunosuppressive IL-10 and TGFβ, as well as other anti-inflammatory mediators." (PMID 26177198, 2015).
tumor (continued). "The therapeutics of possible underlying mechanisms are the improvement of the tumor microenvironment through the suppression of NF-κB and subsequent cytokines such as TGF-β, IL-10, VEGF, COX-2, CCL2 and CCL22, and enhancement the function of transferred CD8+ T-cells." (PMID 26683520, 2015). "One example of this regulation is the macrophage polarization driven by tumor microenvironment towards a suppressive phenotype or the known type 2 macrophage (M2) which is a consequence of presence of immunosuppressive factors (e.g., IL-10 and TGF-β)." (PMID 26347589, 2015). "Third, by RT-qPCR analyses, TANs showed downregulation of anti-tumor genes (e.g., il4, il6, il8, il10, il12, and tnfa) and upregulation of pro-tumor genes such as il1b, which also promotes early cancer angiogenesis, indicating a potential role of TANs in pro-angiogenesis in HCC initiation." (PMID 25828472, 2015). "TGF-β and IL-10 are the most well-known immunosuppressive molecules produced by tumor cells." (PMID 25992978, 2015). "Because there are many cytokines in the tumor microenvironment, including IL-4, IL-6, IL-10, and IL-13, we next asked whether these cytokines down-regulated miR-146a and miR-222 in late tumor TAMs." (PMID 26689540, 2015). "Therefore, it has been proposed that IL-10 plays a key role in the oncogenetic and metastatic ability of neoplasms." (PMID 26783377, 2015). "Indeed, in the MMTV-PyMT mammary tumor model, TAM-derived IL10 indirectly blocks anti-tumor CD8+ T cell activity by suppressing IL12 expression by intratumoral DCs upon paclitaxel treatment." (PMID 26500653, 2015). "Interleukin (IL)-24 is a novel tumor suppressor and a member of the IL-10 cytokine superfamily." (PMID 26009991, 2015). "Within the tumor microenvironment, the immunosuppressive milieu is further enhanced by the production of interleukin 10 (IL-10), which together with IL-4, IL-6, and IL-13 cytokines induces monocyte differentiation toward a mature M2-polarized phenotype that is characteristic of TAMs." (PMID 28536400, 2015). "At a later timepoint, a phenotypic shift may occur and be responsible for the accumulation of anti-inflammatory, but proangiogenic M2 macrophages, which secrete IL-10, within the tumor mass." (PMID 26132316, 2015). "However, not all NK cells control tumor growth, as certain subpopulations of NK cells can also suppress tumor immunity by producing immune suppressive cytokines (e.g., IL-10, IL-13) and promoting the growth of regulatory T cells (Tregs)." (PMID 29061951, 2015). "A2B receptor stimulation enhances IL-10 production in tumor tissue." (PMID 26317647, 2015). "From a therapeutic standpoint, it is also important to elucidate how IL-10 might interact with other cytokines in the microenvironment to generate an anti-tumor or pro-tumor response." (PMID 26217588, 2015). "It is possible that A2B stimulation could enhance IL-10-mediated STAT3 activation in at last some cell types in our tumor model." (PMID 26317647, 2015). "Also the release of IL-10 by both tumor cells and TAMs immunosuppresses cytotoxic T-lymphocytes (CTLs)." (PMID 26243145, 2015). "These Tregs might tolerize tumor infiltrating antigen presenting cells through IL-10 induced immunoglobulin-like transcripts (ILT)-2, ILT3, ILT4, and decreased expression of CD40, CD80, and CD86 costimulatory molecules." (PMID 25972872, 2015). "Although prostaglandins, IL-10, and TGF-β that are produced by TAMs (tumor-associated macrophages, a type of polarized M2 macrophage) are known to be immunosuppressive mediators produced by these macrophages, the possible presence of other mediators has not yet been fully addressed." (PMID 26599209, 2015). "IL–10 shows its bidirectional functions both in pro-tumor and anti-tumor effect." (PMID 26440936, 2015). "Increases in serum IL-10 levels, and tumor-infiltrating CD8+ T cells, and decreases in PBMC CD4+ populations after NHS-IL12 treatment were linked to exposure and may be evaluable as biomarkers in the future." (PMID 26091536, 2015).
tumor (continued). "STAT3 is required for expression of DC-SIGN on macrophages that might help tumor progression because these cells releasing IL-10 favor the maintenance of an activated STAT3 in a tumor context." (PMID 26074923, 2015). "Interestingly, the transcription of the IL-10 gene in tumor cells is indirectly regulated by miR-30d, which acts by directly repressing GALNT7." (PMID 25743773, 2015). "Once in the tumor, these precursors develop into immature DC or tumor-associated macrophages under the influence of VEGF and other immunosuppressive soluble factors, such as IL-10 and TGF-β." (PMID 26442214, 2015). "The tumor immunogenicity could also be shut by high levels of immune suppressive cytokines including transforming growth factor-β (TGFβ), tumor necrosis factor-α (TNFα), and IL10, in the tumor microenvironment." (PMID 26579545, 2015). "Thus, it is possible that HA contributes to immunosuppression and therapeutic resistance through modulation of IL-10 in the tumor microenvironment." (PMID 26106384, 2015). "IL-10 also exerts important anti-angiogenic effects by suppressing cytokine promoters of angiogenesis, which in certain pre-clinical tumor models has been shown to inhibit tumor growth." (PMID 26217588, 2015). "Paradoxically, IL-10 can also exert pro-inflammatory and anti-tumor effects." (PMID 26217588, 2015). "This strategy may also dovetail with recent experimental evidence that therapeutic blockade of IL-10 enhances primary tumor responses to paclitaxel." (PMID 25905470, 2015). "Likewise, reduced M2 features (expression of CD163 and production of IL-10) were found after crosslinking CD16 on the surface of monocytes to cetuximab-coated tumor cells." (PMID 26579227, 2015). "From these data, we speculated that IL-11 induction at tumour sites is associated with enhanced expression of arginase-1, VEGF, TGF-β, and IL-10, which may be involved in the suppression of T cell responses in the tumour microenvironment." (PMID 28781374, 2015). "Consequently, plasma concentrations of IL-10, the important tumour suppressive cytokine, were elevated in PC patients (statistically significant) compared to that of both healthy and benign controls." (PMID 24520352, 2014). "A gene-therapeutic approach using interleukin(IL)-4- or IL-10-transfected NIH3T3 cells did not decrease the joint inflammation as expected but in contrast caused an joint-destroying tumor." (PMID 25546418, 2014). "In addition, tumor cells can secrete suppressive factors (IL-10, TGF-β and IDO), express immune inhibitory molecules (FasL and PD-L1), directly inhibit tumor-specific T-cell expansion and proliferation, or induce T-cell apoptosis." (PMID 25231413, 2014). "IL-10 deficiency increases the production of IL-1 (a pro-inflammatory cytokine) and in the absence of IL-10, IL-1 promotes tumor growth in mice." (PMID 25056661, 2014). "IL-10 is therefore found to inhibit the antitumour activities of AMs and may contribute to tumour progression." (PMID 26316944, 2014). "The present study demonstrated that CD45 activation is important in tumor- and IL-10-induced tDCs." (PMID 25013476, 2014). "We are therefore curious as to whether IL-10 produced by TAMs may contribute to the immunosuppressive tumor environment, and this feature of TAMs will be studied in our future research." (PMID 24885636, 2014). "In summary, we demonstrated that ipilimumab can improve ATC proliferation, enhance the BiAb-mediated tumor-specific cytotoxicity, and increase cytokine synthesis, while it attenuates Treg activity as shown by decreased level of IL-10 secretion and reduced Treg population." (PMID 25008236, 2014). "Besides its direct effects on tumor progression, galectin-1 also plays a role in tumor immune regulation by creating a bias toward a Th2 profile and activation of tolerogenic DC and IL-10 producing regulatory (Tr1) cells." (PMID 24658839, 2014). "In contrast, a combination of TRAIL, IL-10, and IL-12 can lead to tumor suppression." (PMID 24955376, 2014).
tumor (continued). "However, overall the tumor cell supernatants induced a more M2 prone phenotype with relatively high expression levels of IL-10 and low expression levels of M1 markers: IL-12, CD80 and HLA-DR." (PMID 25192022, 2014). "It is thus conceivable that once recruited to the MM microenvironment, monocytes are exposed to tumor- and stroma-secreted factors (such as IL-10, hypoxia) and may acquire characteristics of alternative M2 polarization." (PMID 25526031, 2014). "It has been speculated that IL-10 contributes to the escape of tumor cells from immune surveillance and that it favors tumor growth." (PMID 24765208, 2014). "We cannot define the source of high IL-10 levels in our study; it could be Th2, T-reg, or tumor cells." (PMID 25541655, 2014). "In addition to the cytokines that are known to induce MDSC accumulation, we also found an increase in serum levels of IFNγ and IL-10 in several tumor models." (PMID 25401795, 2014). "In addition, CTL-derived cytokines, including tumor necrosis factor α, interleukin 4 (IL-4) and IL-10, contribute to tumor rejection by inhibition of tumor stroma formation." (PMID 25289108, 2014). "This may be an effect of overall tumor burden possibly due to an immunosuppressive function of the tumors, e.g. due to the production of immunosuppressive cytokines like TGFβ and IL-10 or the expression of Fas ligand on the tumor cell surface." (PMID 25121970, 2014). "Recent experiments in vitro and in vivo have shown that cancer cells transfected with IL-27 activate CD8+ T cells to promote the secretion of anti-tumor cytokines Interleukin-10, although, at the same time, IL-27 inhibits the secretion of Interferon- by CD8+ T cells." (PMID 24633175, 2014). "Furthermore, the STAT3 activity in tumor cells enhances the expression of several immune-suppressing soluble factors, such as IL-6, IL-10 and VEGF, all of which are known to prevent the maturation of dendritic cells." (PMID 24995504, 2014). "On the other hand, anti-inflammatory macrophages secrete IL-10 which promotes tumor growth." (PMID 24633175, 2014). "Blockage of IL-10 signaling may lead to enhanced inflammation and increased number of Tregs and MDSCs, which inhibit tumor immunity, allowing tumors to grow." (PMID 25056661, 2014). "IL-10 has been reported to be both “pro-tumorigenic” by inhibiting tumor cell lysis by cytotoxic T cells and “anti-tumorigenic” by promoting NK-cell-mediated tumor clearance and inhibiting angiogenesis." (PMID 25101088, 2014). "Moreover, the mRNA expression of IL-4 and IL-10 in tumor tissue and pleural effusion of NSCLC patients was significantly higher than that of IL-2, IL-12, and INF-γ." (PMID 24872958, 2014). "This evidence suggests that IL-10 production by tumor cells inhibits metastasis." (PMID 24901008, 2014). "Additionally, IL-10 expression was also investigated using immunohistochemistry in primary tumor tissues." (PMID 24762057, 2014). "Because this effect was proportional to the numbers of type I NKT cells added in vitro, it would be interesting to see if greater quantities of NKT cells in vivo would shift the equilibrium in immune reaction to SAA-1 further, decreasing IL-10 mediated suppression, and restoring tumor immunity." (PMID 25389427, 2014). "On the other hand, TLR agonists have immune inhibitory effects as evidenced by the induction of several immune suppressive factors, including IL-10, T regulatory cells (Treg), and PD-L1, all of which could dampen anti-tumor immunity." (PMID 24624132, 2014). "This indicated that the personalized probiotics based on the ratio of IFN-γ/IL-10 strategy could be a promising methodology to activate or restore the tumor killing capability of human peripheral immune system." (PMID 25759833, 2014). "In malignancy, this might imply a priori that IL-10 might promote tumour development, by acting to suppress anti-tumour immune responses." (PMID 25177683, 2014).